MTOR (mechanistic target of rapamycin kinase)
Diseases named in the same sentence as MTOR in open-access papers (continued):
Sharing a sentence is not in itself a finding about the gene and the disease.
pancreatic cancer (continued). "For example, rapamycin, an FDA-approved mammalian target of rapamycin inhibitor (mTOR), reduced the viability of CD133+ cells in pancreatic cancer spheroids." (PMID 38737455, 2024). "The use of mTOR inhibitors and SESN2 expression vectors in this study clearly demonstrated that SESN2 promotes glycolysis in pancreatic cancer through the mTOR signaling pathway." (PMID 39595578, 2024). "In pancreatic cancer, ALKBH5 has been shown to directly modulate DDIT4-AS1, promoting the proliferation and metastasis of pancreatic cancer cells by inhibiting mTOR signaling." (PMID 39468015, 2024). "Blue LED irradiation suppressed pancreatic cancer cell and tumor growth by regulating AKT/mTOR signaling." (PMID 39439950, 2024). "The heterogeneity of pancreatic cancer is marked by extensive genomic, proteomic, and epigenetic alterations affecting various core signaling pathways, such as RTKs, TGF-β receptor, Akt-mTOR, SWI/SNF complex, Wnt/Notch, JNK, and Hippo signaling." (PMID 39349432, 2024). "Qingyihuaji Formula, a traditional Chinese medicine, alleviates pancreatic cancer by modulating autophagy via MAPK/ERK and PI3K/Akt/mTOR pathways." (PMID 39403146, 2024). "In pancreatic cancer, RAGE-mediated autophagy acts by reducing the phosphorylation level of mammalian target of rapamycin (mTOR) and limiting the formation of the Beclin-1/VPS34 autophagy complex." (PMID 38529373, 2024). "In our study, we found enrichment of the PI3K/AKT/mTOR pathway in the differentially expressed gene functions between the high and low expression groups of GGCT in pancreatic cancer samples." (PMID 38914714, 2024). "In pancreatic cancer, the PI3K/AKT/mTOR pathway frequently undergoes dysregulation due to genetic alterations." (PMID 39087024, 2024). "Targeting mTOR signaling to prevent adaptive resistance to KRAS inhibitors has also been reported for non-small cell lung cancer and pancreatic cancer models." (PMID 38992135, 2024). "Apoptotic death and inhibition of pancreatic cancer stem cells were unveiled by TQ via Notch1 and PI3K/Akt/mTOR-regulated autophagy signaling pathways." (PMID 38532470, 2024). "Our study confirmed that overexpression of NLK increased the expression of p-PI3K (Tyr458), p-AKT (Ser473), and p-mTOR (Ser2448) in vitro, while knockout of NLK suppressed the PI3K/AKT/mTOR signaling pathway and inhibited EMT in pancreatic cancer cell lines." (PMID 39097735, 2024). "The high expression of NLK activates the PI3K/AKT/mTOR and EMT signaling pathways, promoting the invasion and migration of pancreatic cancer cells." (PMID 39097735, 2024). "In pancreatic cancer cells, ALDH1A3 increases the expression of HK2 by its activation of the PI3K/AKT/mTOR pathway." (PMID 39251846, 2024). "Collectively, our study highlights Gαi3’s multifaceted role in promoting pancreatic cancer growth through the modulation of Akt-mTOR and PKA-Hippo-YAP signaling pathways, as well as its influence on the immune landscape within the pancreatic cancer TME." (PMID 39349432, 2024). "In pancreatic cancer (PAAD), the RNA-binding protein FUS (FUS)-induced circular RNA (circRNA), circRHOBTB3, has been shown to aberrantly inhibit NACC1/Akt/mTOR signaling." (PMID 39769395, 2024). "Previous research has shown SGLT2 inhibitors to have antiproliferative effects against different types of tumors, including pancreatic carcinoma, due to their blockage of glucose reuptake in cells and suppressing glycolysis via the PI3K/AKT/mTOR pathway." (PMID 38611003, 2024). "Pharmacological inhibition of mechanistic target of rapamycin (mTOR), a protein kinase that acts as a key mediator of several growth factors, mimics the effect of serum starvation in PANC-1 cells and other pancreatic carcinoma cells." (PMID 39397076, 2024). "Together, overexpressed MXRA5 is important for pancreatic cancer cell growth possibly through promoting EMT and Akt-mTOR activation." (PMID 36828810, 2023).
pancreatic cancer (continued). "In liver and pancreas cancer models, UTX can control the expression of negative regulators of mTOR such as DEPTOR, and its disruption prevents their transcription and facilitates tumorigenesis through increased mTORC1 activity." (PMID 37261974, 2023). "Rapamycin also significantly reduces pancreatic tumor growth and mTOR-related signaling and can normalize elevated serum leptin levels through the PI3K/mTOR signaling pathway." (PMID 37444627, 2023). "Multiple signaling pathways are vital for pancreatic cancer initiation and progression, including RAF/MEK/ERK, PI3K/Akt/mTOR, Wnt/Notch and NFκB signaling etc." (PMID 36828810, 2023). "For example, CXCL12/CXCR7 can activate Rho/ROCK pathway and promote the migration and invasion of pancreatic cancer cells; CXCL12/CXCR7 promotes the malignancy of renal cancer cells by activating mTOR signaling pathway." (PMID 35226830, 2022). "LKB1 is also regulated by miR-7 in pancreatic cancer in which it has been shown that miR-7 overexpression reduces AMPK activation and promotes mTOR signaling with consequent autophagy inactivation, and reduced Warburg effect in pancreatic cancer cells." (PMID 35309939, 2022). "In summary, we found that ERAP2, a previously unreported biomarker, predicts sensitivity to gemcitabine in patients with pancreatic cancer, possibly acting in part through the PI3K/AKT/mTOR signaling pathway." (PMID 36214762, 2022). "For instance, Liu has reported that lncRNA NR2F1-AS1 promotes proliferation and invasion of pancreatic cancer by regulating the neighboring NR2F1 gene and activating AKT/mTOR signaling pathway." (PMID 36186449, 2022). "Our findings suggest that miR-301a activates two major cell proliferation pathways, Tsc1/mTOR and Gadd45g/Stat3, in vivo, to facilitate development of inflammatory-induced PanIN and maintenance of PSC activation and desmoplasia in pancreatic cancer." (PMID 35211358, 2022). "In conclusion, identification of HDACs/mTOR inhibitor as a synergistic inhibitor, provides a potent therapeutic strategy that targets HER2-positive pancreatic cancer." (PMID 36457011, 2022). "Another study revealed that MAPK (87%), PI3K/AKT/mTOR (19%), DNA repair (15%), cell cycle (11%), and AKT/mTOR (19%) pathway alterations were present in pancreatic cancer patients." (PMID 35664782, 2022). "In conclusion, our study has provided evidence supporting that the HGF/c-Met signaling pathway promotes PNI in pancreatic cancer by activating the mTOR/NGF axis and increasing the invasion and migration ability of pancreatic cancer cells." (PMID 35449152, 2022). "In pancreatic cancer, Li and colleagues found that PDP1 promotes pancreatic cancer proliferation and invasion through regulating the MAPK/mTOR signaling pathway." (PMID 36276992, 2022). "Our previous study demonstrated that Periplocin inhibited pancreatic cancer cell proliferation and induced apoptosis by activating the AMPK/mTOR pathway and inhibiting p70S6 kinase." (PMID 35847371, 2022). "ASA has been reported to inhibit the PI3K/Akt/mTOR signaling pathway to mitigate GEM resistance and EMT in pancreatic cancer cells." (PMID 35892853, 2022). "The wound healing and Transwell-based assays showed that, compared with the sh mTOR group, HGF recovered the migration and invasion abilities of pancreatic cancer cells in the HGF + sh mTOR group." (PMID 35449152, 2022). "In pancreatic cancer treatment, ginsenoside Rg3 regulated the survival of pancreatic cancer cells via the PI3K/Akt/mTOR pathway." (PMID 35684449, 2022). "Activation of AMPK/mTOR signalling by irisin was also found to inhibit EMT by increasing E‐cad expression and decreasing vimentin expression in pancreatic cancer." (PMID 36251949, 2022). "It was demonstrated that irisin treatment activates the AMPK pathway and downregulates the mTOR pathway, thereby suppressing pancreatic cancer cell growth, and thus inhibits the epithelial–mesenchyme transition (EMT) of pancreatic cancer cells." (PMID 35164383, 2022).
pancreatic cancer (continued). "We also found that compared with the sh mTOR group, activating the HGF/c-Met signaling pathway recovered the N-cadherin and Vimentin expression of pancreatic cancer cells but decreased the E-cadherin expression in the HGF + sh mTOR group." (PMID 35449152, 2022). "Here, we investigated the therapeutic utility of everolimus (Evr), an inhibitor of mammalian target of rapamycin (mTOR), in targeting the Warburg effect to overcome GEM resistance in pancreatic cancer." (PMID 33849427, 2021). "In pancreatic cancer, MFN2 has been demonstrated to induce autophagy through inhibition of the PI3K/Akt/mTOR pathway." (PMID 34956177, 2021). "Fisetin in murine xenograft pancreatic cancer PANC‐1 cells inhibits PANC‐1 cell proliferation, enhances AMPK/mTOR signaling pathway and stress‐induced transcription factor p8, induces autophagy, and increases the ATF4 and ATF6." (PMID 33473265, 2021). "In this regard, strategies based on mTOR inhibition and/or AMPK activation have been shown to sensitize pancreatic cancer cells to GEM." (PMID 34959348, 2021). "Evr has been shown to promote the apoptosis of GEM-resistant (GEMres) pancreatic cancer cells by activating caspase-3 and caspase-7 through PI3K/AKT/mTOR signaling." (PMID 33849427, 2021). "AZD has also been shown to inhibits pancreatic cancer growth and metastasis through ROS-mediated apoptosis, and also induces autophagy and apoptosis via AKT/mTOR/Atg5 pathways." (PMID 34944759, 2021). "Previous reports have shown evidence of the combined anti-tumor effects of mTOR inhibition and GEM in pancreatic cancer." (PMID 33849427, 2021). "Taken together, Evr plays an essential role as an mTOR inhibitor and can be considered as an adjuvant or complementary agent to GEM, as its therapeutic effects against GEM-resistant pancreatic cancers have been further clarified." (PMID 33849427, 2021). "In pancreatic cancer, overexpression of sestrin 2 promoted PANC-1 cells proliferation and increased glycolysis, and mTOR inhibitors suppressed these effects in vitro." (PMID 34784907, 2021). "miR-590 suppressed proliferation and induced apoptosis of pancreatic cancer by targeting HMGA2 and inhibiting the phosphorylation of mTOR." (PMID 34856955, 2021). "Periplocin inhibits human pancreatic cancer cell proliferation and induces their apoptosis by activating the AMPK / mTOR pathway." (PMID 33231372, 2021). "Mechanistically, the elevated LDHA expression and enhanced L‐lactate production fuelled pancreatic cancer growth and progression, and the activity depends on the AMP‐activated protein kinase (AMPK)/ mammalian target of rapamycin (mTOR) signaling pathway." (PMID 34185423, 2021). "In summary, periplocin inhibits mTOR through AMPK activation, thereby, suppressing the proliferation of pancreatic cancer cells, their migration, and invasion." (PMID 33231372, 2021). "In conclusion, we revealed that Evr effectively impaired the growth of GEM-resistant pancreatic cancer cells, both in vitro and in vivo, by regulating the PI3K/AKT/mTOR signaling pathway." (PMID 33849427, 2021). "Previous studies indicated that multiple signal pathways regulate pancreatic carcinoma cell apoptosis or proliferation, including PI3K-akt-mTOR signal pathway, AMPK-Akt signal pathway or Wnt signal pathway." (PMID 33661942, 2021). "Irisin administration reportedly suppresses pancreatic cancer cell growth via the activation of AMPK and downregulation of the mTOR pathways, thereby inhibiting EMT of pancreatic cancer cells." (PMID 32257109, 2020). "In pancreatic cancer cells, overexpression of SLC41A1, a membrane protein for Mg2+ extrusion, and the resulting low [Mg2+]i, inhibited the Akt/mTOR pathway and cancer proliferation." (PMID 32927908, 2020).
pancreatic cancer (continued). "Antroquinonol has been demonstrated to exhibit inhibitory effects on non-small cell lung cancer (NSCLC), as well as human pancreatic cancer, PANC-1 and ASPC-1, via the PI3K/Akt/mTOR pathway." (PMID 33228222, 2020). "In particular, previous study showed that suppression of PI3K/mTOR inhibited the expression of EHMT2, which is a H3K9 methyltransferase, therefore enhancing the therapeutic response in pancreatic cancer." (PMID 32660632, 2020). "Previous reports have reported that miR-1271, as a tumor suppressor in pancreatic cancer, promoted apoptosis through the reduction of AKT/mTOR signaling." (PMID 33015162, 2020). "PI3K/Akt/mTOR is often activated in malignancies, and the Ras/Raf/MEK/ERK signaling pathway is enhanced in pancreatic cancer, colon cancer, and thyroid cancer." (PMID 32498447, 2020). "S6 is a downstream molecule of the PI3K/Akt/mTOR pathway, and phosphorylation GLUT1 expression and S6 phosphorylation were examined in five pancreatic cancer cell lines by Western blotting." (PMID 33005852, 2020). "This binding allows the activation of numerous signaling pathways in pancreatic cancer cells, such as phospholipase C, MAPK, and PI3K-Akt-mTOR, as well as JAK/STAT pathways." (PMID 31275385, 2019). "A recent study found that HNSCC with histological PNI had increased levels of Akt/PKB and mTOR kinase activation, and the Akt pathway has also been found to play a role in PNI in pancreatic cancer." (PMID 31214495, 2019). "The autophagy activation of Rotten was found in prostate and pancreatic cancer stem cells, and results indicated this activation effect was dependent on the Akt/PI3K/mTOR pathway." (PMID 30870998, 2019). "Western blotting, caspase-3 activity measurement, and CCK-8 and reactive oxygen species (ROS) assay were used to examine the effects of Mfn2 on pancreatic cancer autophagy, apoptosis, cell proliferation, oxidative stress, and PI3K/Akt/mTOR signaling." (PMID 30046371, 2018). "Then, the upregulated LDHB could activate glycolysis and decrease GEM sensitivity in pancreatic cancer, and the increased glutamine synthetase and decreased glutaminase could further increase the level of intracellular glutamine, which is indispensable for mTOR activation." (PMID 30419950, 2018). "In conclusion, CuB treatment had a strong growth inhibitory effect in pancreatic cancer cells by decreasing EGFR levels and downstream signaling of PI3K/Akt/mTOR and STAT3." (PMID 29262554, 2017). "In line with this, it was recently proposed that stimulation of ACKR3 with CXCL12 leads to the activation of mTOR and Rho/ROCK pathways promoting cell migration and liver metastasis of pancreatic cancer cells." (PMID 29156704, 2017). "In this study, we demonstrate for the first time that CuB inhibits pancreatic cancer cell proliferation by interfering with EGFR levels and downstream signaling of PI3K/Akt/mTOR and STAT3." (PMID 29262554, 2017). "Another study dealing with human pancreatic cancer revealed an inhibitory effect on tumorigenic cancer stem cells through the combined blockade of HH and mTOR signaling using SMO and mTOR inhibitors together with standard chemotherapy." (PMID 28122581, 2017). "These genes were most significantly enriched in well-known oncogenic pathways associated with tumor growth, survival, and metastasis, including the mTOR, renal cell carcinoma, adherens junction, Wnt, VEGF, and pancreatic cancer pathways." (PMID 28088786, 2017). "In pancreatic cancer, overexpressed EGFR regulates downstream signaling activation, including PKC, PI3K/AKT/mTOR, SRC, STAT and RAS/RAF/MEK1/ERK1/2, and regulate numerous EGFR-interacting proteins." (PMID 27399694, 2016). "This is the first report of the efficient elimination of pancreatic cancer stem-like cells by the double blockage of Hh/GLI and mTOR signaling." (PMID 27349387, 2016).
pancreatic cancer (continued). "Recent efforts have identified multiple dysregulated signaling pathways in pancreatic cancer development and progression, many of which appear to be reasonable targets including PI3K/mTOR, SIRT1, and ALK." (PMID 26369833, 2015). "We further elucidated the downstream signaling pathways that HNF1A exerts its tumor suppressor function in pancreatic cancer and found that HNF1A knockdown activated Akt/mTOR signaling pathway." (PMID 25793983, 2015). "Most studies suggest that metformin acts through its effect on mTOR and MAPK signaling activation for anticancer actions in pancreatic cancer." (PMID 26391180, 2015). "The marked responses observed in Pc1Pik3cap110* pancreatic cancers indicate great promise for the use of agents targeting the PI3K cascade, such as dual PI3K/mTOR inhibitors." (PMID 26436951, 2015). "Half of human PDACs present pancreatic cancer cells which have lost expression of the negative regulator of translation 4E-BP1, rendering them insensitive to mTOR inhibitors." (PMID 25834145, 2015). "To elucidate the molecular mechanisms modulated by HNF1A inactivation in pancreatic cancer cells, we investigated the impact of HNF1A knockdown on AKT/mTOR signaling pathway." (PMID 25793983, 2015). "miR-373 regulates MMP activity by modulating MAPK signaling or targeting mTOR and SIRT1 in human fibrosarcoma cells, and by targeting ZIP4 in pancreatic cancer." (PMID 26103880, 2015). "The mTOR inhibitor RAD001 alone, or together with EHT5372, reduced pancreatic cancer size 30-fold, while the drug combination reduced the number of microscopic tumor foci 2-fold compared to RAD001 alone." (PMID 25352950, 2014). "In contrast, [177Lu-DOTA-Tyr3]-octreotate was shown to be less effective when combined with the mTOR inhibitor everolimus (RAD001, Novartis) in a rat model of pancreatic cancer." (PMID 24528513, 2014). "The focus of this brief article is on the central role of the mechanistic/mammalian target of rapamycin (mTOR) in mediating insulin/IGF-1 and G protein-coupled receptor (GPCR) signaling leading to proliferation of pancreatic cancer cells." (PMID 25295009, 2014). "This is particularly true for pancreatic tumors expressing very low levels of 4E-BP1 and 4E-BP2 and which are resistant to mTOR inhibitors." (PMID 25594050, 2014). "PM inhibited p-Akt and its downstream targets Foxo-3α and cyclin D1; NF-κB (p65) and NF-κB-regulated Cox-2 and VEGF; p-mTOR and mTOR-regulated p-S6K1 and p-4E-BP1 in both pancreatic cancer cell lines." (PMID 24603988, 2014). "The PI3K/Akt/mTOR pathway plays a pivotal role in promoting the proliferation and survival of PDAC cells, is activated in pancreatic cancer tissues, and limits catabolic processes, including autophagy." (PMID 25295009, 2014). "The mTOR inhibitor, rapamycin, reduced the viability of CD133+ pancreatic cancer cells and sphere formation which is an index of self-renewal of stem-like cells, indicating that the mTOR pathway functions to maintain cancer stem-like cells." (PMID 24231729, 2013). "Rational targets for this combined approach in pancreatic cancer are EGFR and mTOR, leading to synergistic anticancer activity as has been demonstrated in pre-clinical models." (PMID 22367239, 2013). "Our results not only provide some new clues for mTOR upregulation in radiation-treated pancreatic clinical samples and cell lines, but also demonstrated that miR-99b played important roles in pancreatic cancer radioresistance and maybe a candidate therapeutic target for pancreatic cancer." (PMID 23886294, 2013). "The screening revealed that the mTOR inhibitor rapamycin can effectively reduce the growth and/or viability of CD133+ pancreatic cancer cells." (PMID 24231729, 2013). "Therefore, mTOR might be a promising target to eliminate pancreatic cancer stem cells." (PMID 24231729, 2013).